IRS1 (insulin receptor substrate 1)
Diseases named in the same sentence as IRS1 in open-access papers (continued):
Sharing a sentence is not in itself a finding about the gene and the disease.
Insulin resistance (continued). "The transient increased DAG content temporally caused insulin resistance by increasing protein kinase C-θ (PKC-θ) activation and inhibiting insulin-stimulated IRS-1 tyrosine phosphorylation and AKT2 phosphorylation." (PMID 41009753, 2025). "This impairment leads to the prolonged activation of IRS-1, which triggers harmful feedback mechanisms to mitigate excessive IRS-1 overactivity and brain insulin resistance." (PMID 40362446, 2025). "The deletion of any novel PKC family members decreases IRS-1 Ser-307 phosphorylation, reducing liver and skeletal muscle insulin resistance." (PMID 40141412, 2025). "IL‐6 triggers insulin resistance by disrupting insulin signaling and glucose transport, primarily through downregulation of IRS‐1 and GLUT‐4." (PMID 40551726, 2025). "ROS can inhibit the function of IRS-1 (insulin receptor substrate-1), leading to the blocking of insulin signaling pathways and exacerbating insulin resistance." (PMID 40442740, 2025). "Low levels of adiponectin cannot maintain inhibited NF-κB nuclear translocation, which increases insulin receptor substrate-1 (IRS-1) serine phosphorylation-producing insulin resistance." (PMID 40243433, 2025). "Beyond miRNAs, lncRNAs such as KCNQ1OT1 play a chromatin remodeling role by recruiting Polycomb repressive complexes to the promoter region of IRS1, thereby silencing its transcription and amplifying systemic insulin resistance." (PMID 40747301, 2025). "Studies have demonstrated that berberine enhances cellular insulin sensitivity and ameliorates insulin resistance by modulating key components of the insulin signaling pathway—including InsR, IRS-1, AKT, and AMPK." (PMID 41471379, 2025). "This process also occurs in IRS-1 (Insulin Receptor Substrate 1), which consequently leads to hyperglycemia induced by insulin resistance." (PMID 40904859, 2025). "Stress Kinase (JNK) and transcription factor Nuclear Factor kappa B (NF-κB) activation and phosphorylation actively induce insulin resistance via Insulin Receptor Substrate 1 (IRS1) disruption." (PMID 40951640, 2025). "Upregulation of the IRS-1 pathway in the three key insulin target tissues is related to insulin resistance and impaired glucose metabolism, including gluconeogenesis and glycogen synthesis." (PMID 40729355, 2025). "In one study, prolonged exposure of skeletal muscle in vitro to high concentrations of BCAA leads to insulin resistance due to impaired IRS1/AKT signaling." (PMID 40431415, 2025). "LPS-induced iNOS drives nitrosylation of IRβ, IRS1, and AKT, which blunts insulin-stimulated phosphorylation and causes insulin resistance." (PMID 41373704, 2025). "TNF-α promotes hepatocyte insulin resistance via JNK-1–mediated phosphorylation of IRS-1, which disrupts downstream PI3K/AKT signaling and impairs glycogen synthesis." (PMID 40988029, 2025). "Our data showed that PPD attenuated PA-induced insulin resistance by regulating the IRS-1/PI3K/Akt signaling pathway in the three cell lines (C2C12, HepG2, 3T3L1)." (PMID 40729355, 2025). "Hepatic insulin resistance was seen in HFD rats supported by downregulation of IRS-1/Akt protein expression." (PMID 40141836, 2025). "Hyperexpression of miR-15b blocks IRS1 insulin receptors in hepatocytes, contributing to the development of hepatic insulin resistance." (PMID 40217882, 2025). "We previously revealed that senescent endothelial cells induce adipocyte senescence in WAT, reducing Irs1 expression-mediating systemic insulin resistance through Il1a-mediating SASP secretion in EC-specific progeroid mice." (PMID 40822955, 2025). "Serine phosphorylation of IRS-1 inhibits this insulin signal transduction and thus results in insulin resistance." (PMID 40274715, 2025).
Insulin resistance (continued). "IL-6 was reported to induce insulin resistance by inhibiting transcription or reducing phosphorylation of insulin receptor substrate-1, while elevated hsCRP was a prestigious biomarker in inflammation and associated tightly with cardiovascular risk." (PMID 38954305, 2025). "Mechanistically, BPs disrupt hepatic lipid homeostasis by activating PPAR-γ and suppressing fatty acid oxidation while concurrently inducing insulin resistance via impaired IRS-1/PI3K/Akt signaling." (PMID 40475995, 2025). "These stress kinases interfere with IRS-1 function, promoting insulin resistance by increasing inflammation-related gene expression and the activation of nuclear factor kappa B (NF-κB) and intensifying insulin resistance." (PMID 40362446, 2025). "mTORC1 hyperactivation can lead to insulin resistance through multiple mechanisms, including the phosphorylation of IRS-1 and the regulation of insulin signaling via Grb10." (PMID 40141237, 2025). "Abnormal phosphorylation of IRS-1 results in decreased sensitivity of insulin binding to InsR and a partial translocation of IRS-1 from the membrane to the cytoplasm, which is a major molecular basis for insulin resistance." (PMID 39966707, 2025). "Elevated hs-CRP impairs the insulin signaling pathway that promotes glucose translocation by phosphorylating the insulin receptor substrate-1, thereby promoting insulin resistance." (PMID 39940942, 2025). "Another mechanism that leads to insulin resistance is the phosphorylation of insulin receptor substrate 1 (IRS-1) serine residues." (PMID 39136514, 2025). "For instance, patients with polycystic ovary syndrome often exhibit reduced levels of IRS1 phosphorylation, which contributes to insulin resistance and ovarian dysfunction." (PMID 40897829, 2025). "LPS, associated with intestinal dysbiosis, is recognized by the TLR-4 receptor which leads to the induction of insulin resistance, mainly through phosphorylation of IRS-1, the main marker of this condition in obesity." (PMID 40260376, 2025). "Boys presented stronger correlations between placental IRS1 expression and fat distribution, while placental IRS1 expression in girls strongly correlated with insulin resistance-related variables." (PMID 40243885, 2025). "BMEE can reduce hepatic insulin resistance and the same time improve hepatic glucose uptake via the insulin and the NF‐kB signaling pathways by increasing IRS‐1 and GLUT‐2 gene expression while reducing gene expression of NFkB in the liver." (PMID 39803222, 2025). "B-amyloid accumulation maintains insulin resistance, through serine phosphorylation of insulin receptor substrate- 1 (IRS-1)." (PMID 41480353, 2025). "JNK promotes insulin resistance by phosphorylating serine residues in insulin receptor substrate-1, and IKKβ contributes to insulin resistance through the transcriptional expression of NF-κB." (PMID 40566527, 2025). "Our previous study also demonstrated the potential benefits of fish oil in ARBD, focusing on insulin resistance by analyzing the insulin receptor substrate 1 (IRS-1)/glycogen synthase kinase-3β (GSK3β) pathway and ceramide concentration levels." (PMID 40563336, 2025). "Insulin resistance is characterized by reduced tyrosine phosphorylation of IRS-1 and increased phosphorylation on serine 312 of IRS-1." (PMID 40137124, 2025). "Experimental validation demonstrated that this food‐derived therapeutic formula alleviates renal fibrosis by synergistically regulating insulin resistance and the IRS1/PI3K/Akt pathway activity through its nutrient‐pharmacological components." (PMID 41323824, 2025). "Palmitic acid induces podocyte insulin resistance via ceramide production and serine 307 phosphorylation of IRS1." (PMID 41009556, 2025). "IRS1 and AKT play a key role in the insulin signaling pathway, and their downregulation is associated with insulin resistance." (PMID 40431415, 2025).
Insulin resistance (continued). "Systemic inflammation is a major cause of insulin resistance, as it activates factors such as NF-κB and JNK kinase, which interfere with insulin signaling through phosphorylation of insulin receptor substrate-1 (IRS-1)." (PMID 40362738, 2025). "Activated astrocytes produce higher levels of proinflammatory cytokines, IL-1β, and interferon-γ (IFN-γ) and show phosphorylation of IRS-1 at Ser616, characteristic of insulin resistance." (PMID 40430434, 2025). "Exendin-4 (Ex-4), a GLP-1RA, improved insulin resistance in neurons through insulin receptor substrate-1 (IRS-1), AKT, and GSK-3β pathways." (PMID 41480353, 2025). "IR-induced ER stress leads to MAPK8 hyperactivation, which phosphorylates and inhibits IRS-1, resulting in systemic insulin resistance.ER stress-alleviators reduce hyperglycemia and systemic IR in obese diabetic mice." (PMID 41567335, 2025). "The development of insulin resistance via insulin receptor substrate 1 (IRS-1) involves IKK-mediated serine phosphorylation, leading to the activation of the IKKβ/NF-κB signaling cascade." (PMID 39704874, 2025). "The altered expression of insulin receptor substrate genes (IRS1/2) suggests the potential development of hepatic insulin resistance, indicating an imbalance in glucose and lipid metabolism following PFOS exposure." (PMID 40003090, 2025). "HCV core protein can mediate serine phosphorylation of IRS1 to facilitate insulin resistance as well as upregulate SOCS3 and SOCS7, which are known insulin inhibitors." (PMID 41012578, 2025). "Insulin resistance in VSMCs disrupts normal insulin signaling pathways, particularly those involving insulin receptor substrate-1 (IRS-1) and downstream PI3K-Akt signaling." (PMID 40564010, 2025). "Inflammatory pathways and oxidative stress—driven by NADPH oxidase activation and proinflammatory cytokines such as TNF‐α and IL‐6—also contribute to insulin resistance by inducing serine phosphorylation of IRS‐1 and impairing insulin receptor activity." (PMID 41143273, 2025). "Activation of IRE1α also stimulates the activation of c-Jun amino-terminal kinase (JNK) which contributed to decreased phosphorylation of IRS-1 and hepatic insulin resistance in high fat, high sucrose fed-mice." (PMID 41196673, 2025). "This activation results in insulin resistance by compromising the tyrosine phosphorylation of IRS-1 and the glucose transporter type 4 (GLUT4) activity." (PMID 39704874, 2025). "This approach substantially reduced insulin resistance, promoted glucose uptake, and lowered blood glucose levels by activating the IRS1/PI3K/AKT signaling pathway." (PMID 39995417, 2025). "These cytokines interfere with insulin receptor signaling by inhibiting the serine phosphorylation of IRS1, ultimately contributing to systemic insulin resistance." (PMID 40981178, 2025). "Brain insulin resistance results from impaired insulin signaling, mainly through the insulin receptor substrate 1 (IRS-1)/phosphatidylinositol 3-kinase (PI3K)/protein kinase B (Akt) pathway." (PMID 40362446, 2025). "In a palmitate-induced insulin resistance model involving HepG2 cells, celastrol upregulated the expression of miR-223, restored the levels of glucose transporter type 4/IRS1, and thereby enhanced insulin signaling." (PMID 40897829, 2025). "Both insulin resistance and hyperglycemia have been reported to downregulate IRS1 via increased ubiquitination and serine phosphorylation." (PMID 40940776, 2025). "Type 2 diabetes (T2D) has a feature whereby polymorphisms in genes including IRS1 (Insulin Receptor Substrate 1) and IRS2, which regulate insulin signaling routes, define insulin resistance." (PMID 40430848, 2025).
Insulin resistance (continued). "The pro-inflammatory cytokine IL-6 contributes to insulin resistance through serine/threonine phosphorylation of IRS-1, thereby disrupting insulin signal transduction." (PMID 40959695, 2025). "These cytokines disrupt the IRS-1/PI3K/AKT signaling pathway by inhibiting IRS-1 phosphorylation, impairing glucose metabolism, and exacerbating insulin resistance." (PMID 40647186, 2025). "Elevated levels of phosphorylated IRS-1 at specific serine residues (IRS-1pS616 and IRS-1 pS636/639) were identified as potential biomarkers of this brain insulin resistance in the hippocampal formation in AD." (PMID 40362446, 2025). "This anti-inflammatory context is critical for restoring insulin signaling, as it prevents inhibitory phosphorylation in IRS-1 serine residues, a central mechanism in the pathogenesis of insulin resistance." (PMID 41471698, 2025). "Integrated network pharmacology and in vivo validation revealed that this formula ameliorates renal injury and insulin resistance in DKD rats by activating the IRS1/PI3K/AKT signaling pathway." (PMID 41323824, 2025). "ADIPOQ and TNFA increase insulin sensitivity and insulin resistance, respectively, through modulation of phosphorylation and activation of IRS-1 (a molecule determining insulin sensitivity2930,31." (PMID 41193585, 2025). "In MASLD, selective insulin resistance develops: IRS-1/lipogenic pathways remain active, while IRS-2/glucose-suppressive pathways are impaired." (PMID 41196673, 2025). "Inflammatory pathways, such as JNK and IKKβ, further induce IRS-1 serine phosphorylation, worsening insulin resistance." (PMID 40373017, 2025). "The transcription of SOCS3, induced by NF-κB, leads to the degradation of IRS1/2 via the proteasome, exacerbating insulin resistance." (PMID 41010046, 2025). "The diet also led to increased serine-phosphorylated IRS-1 indicating insulin resistance, and a decreased expression of PSD-95, a protein related to post-synaptic densities." (PMID 41294899, 2025). "In individuals with insulin resistance insulin signaling is impaired at the level of Insulin Receptor Substrate-1 (IRS-1), leading to decreased glucose transport/phosphorylation/metabolism and impaired nitric oxide synthase activation/endothelial dysfunction." (PMID 41009753, 2025). "A rat skeletal muscle cell line’s stimulation with recombinant leptin decreased the phosphorylation of insulin receptor substrate-1 (IRS-1) and impaired glucose uptake, indicating that leptin promotes insulin resistance." (PMID 39943080, 2025). "Elevated leptin and PAI-1 levels exacerbate insulin resistance, interfere with IRS-1, and negatively impact insulin signaling in PLT membranes." (PMID 39858414, 2024). "Phosphorylation of IRS-1 Ser 322 can be considered as a mecha-nism of insulin resistance, point mutations of IRS-1 Ser322Ala or Ser336A prevented GSK-3 phosphorylation of IRS-1." (PMID 38248343, 2024). "Higher levels of urea nitrogen in people with chronic kidney disease have been shown to induce insulin resistance by activating E3 ubiquitin ligases that specifically conjugate ubiquitin to IRS-1, marking it for degradation by the ubiquitin-proteasome system." (PMID 39125606, 2024). "Exposure to glyphosate also induces skeletal muscle insulin resistance by modulating IRS-1/PI3K/Akt insulin signaling molecules, leading to the development of T2DM." (PMID 38902690, 2024). "In diabetic mice and renal cells exposed to high glucose, reduced IRS‐1 levels caused significant up‐regulation of tumor protein 63 (TP63), which demonstrated the potential of TP63 in regulating IRS‐1 and insulin resistance." (PMID 37927197, 2024). "IL-6 has been demonstrated to induce insulin resistance by impairing the phosphorylation of the insulin receptor and insulin receptor substrate-1." (PMID 39519203, 2024).
Insulin resistance (continued). "Tremblay and coworkers demonstrated that elevated amino acid availability contributes to insulin resistance, partly through the phosphorylation of IRS-1 at Ser1101 mediated by the S6K1 kinase." (PMID 38248343, 2024). "More commonly, reduced tyrosine phosphorylation of IRS1 has been reported in insulin resistance/diabetes." (PMID 39119463, 2024). "The Atp6v0d1AKO mice developed cardiac insulin resistance evidenced by decreased IRS-1/2 expression in hearts." (PMID 38505620, 2024). "This revelation introduces a mechanistic insight into the role of TNFα in eliciting insulin resistance, whereby the activation of S6K kinase serves as a direct mediator responsible for the phosphorylation of IRS-1." (PMID 38248343, 2024). "Omega-3 polyunsaturated fatty acids (n3-PUFAs) can inhibit hepatic steatosis and inflammatory infiltration, and improve insulin resistance in rats by reducing IRS-1 phosphorylation." (PMID 39021599, 2024). "Further, they pointed out the role of hyperuricemia in seeding insulin resistance in cardiac cells via the ROS-insulin receptor substrate-1 (IRS1)/serine or threonine kinase or protein kinase B (Akt) phosphorylation route." (PMID 39015868, 2024). "ERα overexpression improved palmitate-induced insulin resistance, indicated by a decrease in pIRS1-S302 and increases in IRS1, pAKT-S473, and pAKT-T308 protein levels." (PMID 38649684, 2024). "The results showed that the expression of p-IRS1 in the insulin resistance group was increased significantly compared with that in the control group." (PMID 38921004, 2024). "Incubation in high glucose medium for 24 h produced insulin resistance, as measured by decreased insulin-induced tyrosine phosphorylation (activation) of IRS1." (PMID 39119463, 2024). "Multiple serine phosphorylation sites of IRS1 have been indicated to be correlated to insulin resistance, including S302, S307, S636/639, and S110114,26–29." (PMID 38649684, 2024). "None of the treatments significantly affected the expression of IRS-1; however, IRS-1pS612 phosphorylation, the hallmark of insulin resistance, was elevated in MOCK-transfected cells in GDB groups by 34.87% (p=0.0203) compared with control conditions." (PMID 38883605, 2024). "SAT is characterized by more numerous small adipocytes, and it is more insulin-sensitive than VAT due to a higher expression of IRS-1, protecting it from insulin resistance." (PMID 39728000, 2024). "Excessive IL-1β production results in insulin resistance because of a decrease in insulin receptor substrate-1 phosphorylation and reduced IRS-1 expression." (PMID 38945951, 2024). "Meanwhile, pretreatment with APN restored the IRS-1/AKT/eNOS/NO signaling pathway to ameliorate PA-induced vascular insulin resistance." (PMID 39765815, 2024). "Sustained AKT1 activation also indirectly activates mammalian target of rapamycin complex 1 (mTORC1), which inhibits IRS1 and further contributes to insulin resistance in a vicious cycle." (PMID 38029396, 2024). "Kumar and Datta in 2022 demonstrated that the upregulation of H19 in skeletal muscles in mice promoted insulin resistance in type 2 diabetes via increased IRS1 and downregulated HDAC6 expression." (PMID 40176927, 2024). "ADMSCs attenuated insulin resistance through upregulation of IRS1 and downregulation of SREBP-1 and Malat1." (PMID 39500806, 2024). "This metabolic inflexibility of significant decrease in tyrosine phosphorylation of IRS-1 is referred to as insulin resistance." (PMID 39728000, 2024). "The production of IL-1 disrupts insulin signaling and leads to the degradation of insulin receptor substrate-1 (IRS-1) by neutrophils, which has been shown to contribute to insulin resistance (IR)." (PMID 39119009, 2024). "Ser/Thr phosphorylation of IRS-1 induces insulin resistance by interfering with the tyrosine phosphorylation cascade of insulin signaling." (PMID 39796441, 2024).